SPN (sialophorin)
Diseases named in the same sentence as SPN in open-access papers (continued):
Sharing a sentence is not in itself a finding about the gene and the disease.
tumor (continued). "Therefore, SPN-A566V, or other equivalent mutations, could be late events that promote tumor progression by increasing the CSC pool and, eventually, the malignant behavior of the tumor." (PMID 33537097, 2021). "Increased expression of SPN impeded tumor cell clustering with T cells, thereby limiting CD3 bsAb-mediated tumor cell lysis." (PMID 31882897, 2019). "In particular, our findings uncover a role for highly-glycosylated cell surface molecules (SPN and MUC1) in hindering CD3 bsAb-induced T cell-tumor cell clustering and consequent tumor cell lysis." (PMID 31882897, 2019). "Rationale: SPINOPHILIN (SPN, PPP1R9B) is an important tumor suppressor involved in the progression and malignancy of different tumors depending on its association with protein phosphatase 1 (PP1) and the ability of the PP1-SPN holoenzyme to dephosphorylate retinoblastoma (pRB)." (PMID 33537097, 2021). "SPN, a regulatory subunit of PP1A, is a known tumor suppressor." (PMID 34319007, 2021). "Because SPN is not regarded as a hormonally active tumor, specific pancreatic hormones are not found in the cells." (PMID 31209654, 2020). "Since both SPN and MUC1 have been reported to limit T cell contacts with tumor cells in vitro, we hypothesized that tumor cells overexpressing these proteins may be less sensitive to T cell killing as a result of decreased clustering with T cells." (PMID 31882897, 2019). "JeKo-1/SPN and JeKo-1/MUC1 cells, formed approximately half the number of T cell clusters as JeKo-1/NT cells even in isotype control conditions, indicating that SPN and MUC1 repel spontaneous tumor cell/T cell contacts that occur in co-culture conditions." (PMID 31882897, 2019). "Rather, SPN and MUC1 modulate the degree of tumor cell sensitivity." (PMID 31882897, 2019). "However, even if tumor-selective blockade of SPN function proves to be impractical (or not highly effective), SPN expression level might be a useful biomarker for sensitivity to CD3 bsAb therapy." (PMID 31882897, 2019). "Altogether, these data indicate that SPN and MUC1 modulate tumor cell sensitivity to CD20xCD3 bsAb independent of CD20 expression, while increased expression of CD52 directly affects CD20 cell surface levels." (PMID 31882897, 2019). "Our data suggest the possibility that inhibition of SPN function might sensitize cancers to treatment with CD3 bsAb (as well as to other immunotherapies, since SPN significantly affects the ability of tumor cells to cluster with T cells even in the absence of CD3 bsAb)." (PMID 31882897, 2019).
infection (45 papers, 2010 to 2025). The state of being infected such as from the introduction of a foreign agent such as serum, vaccine, antigenic substance or organism. "For example, inflammation in the upper respiratory tract increases the risk of systemic dissemination of SPN, even though it is critical for combating the localized infection at that site." (PMID 26500655, 2015). "Specifically, the ability of GAS to cause both pharyngeal and cutaneous infections correlates with strains producing enzymatically-active SPN, while the ability to cause infection of only the pharynx or skin is associated with GAS strains producing enzymatically-inactive SPN." (PMID 35889195, 2022). "Since SPN is typically considered an extracellular pathogen, we sought to determine the significance of loss of pore forming ability and capacity to adopt an intracellular niche in an in vivo infection scenario." (PMID 33216805, 2020). "Additionally, siRNA-mediated specific knock down of Gal8 in hBMECs (knock-down efficiency ~60%) resulted in significant decrease of LC3 association with WT SPN at 3 h p.i. and considerably improved intracellular recovery of the same following infection at both 6 and 12 h time points." (PMID 30011336, 2018). "Our study demonstrates that during the acute phase of infection, SPN lung titres are over 2-log higher in HDM-exposed mice despite the presence of nearly double the number of BAL macrophages/monocytes in the airways." (PMID 35273509, 2022). "Subarachnoid vessels were identified as the primary contact site of SPN with the brain (at 1 h post-infection), which later spread to the cerebral cortex, septum, and eventually, to choroid plexus (by 8 h post-infection)." (PMID 33224900, 2020). "Following infection of the lower respiratory tract and subsequent bloodstream invasion, SPN breaches the blood–brain barrier endothelium for invasion of the central nervous system." (PMID 33224900, 2020). "We then quantified the intracellular SPN population subsets observed earlier in hBMECs following infection with WT:Ply-High and WT:Ply-Low strains at 3 h p.i. and 9 hp.i." (PMID 30011336, 2018). "Following infection via hematogenous route, WT SPN in the blood displayed enormous heterogeneity in Ply expression, wherein majority of them showed low to negligible Ply levels at 14 h p.i.." (PMID 30011336, 2018). "We also analyzed proliferation of different SPN strains in the mice blood at early time points during the course of infection." (PMID 30011336, 2018). "Next, in order to determine the existence of any intersection between these two eat-me signals, we quantified SPN co-localization events with Gal8 and ubiquitin at different time points post infection." (PMID 30011336, 2018). "In a model of ex vivo infection, SPN bound to an unknown membrane receptor through a putative carbohydrate binding site found in SPN’s N-terminus." (PMID 35889195, 2022). "Early in the course of infection, SPN were found tightly attached to the BBB endothelium; however, these numbers reduce with time with a concomitant increase in the number of SPN present in the brain tissue, suggesting pneumococcal translocation across the BBB." (PMID 33224900, 2020). "The Δply mutant strain exhibited higher survival ability particularly at later time points of 8 and 12 h, wherein it showed 2 and 3.5 fold higher survival efficiency compared to WT SPN without any observable cell death due to infection." (PMID 30011336, 2018). "However, despite this, few WT SPN manage to survive up until 12 h and persistently co-localize with autophagosomes (Gal8+ and LC3+ compartments) till extended hours post infection (8 and 10 h p.i.)." (PMID 30011336, 2018). "Results from their study also illustrated that CMT did not occur during mixed infection with GAS strains producing either SLO or SPN alone, implying that the process of translocation depended on a specific interaction between the two proteins prior to or during secretion." (PMID 35889195, 2022).
infection (continued). "Interestingly, the junctions between the endothelial cells in the subarachnoid space and choroid plexus were found to be intact during the course of infection, suggesting that SPN predominantly adopts the transcytosis route for crossing the BBB, especially in the early stages of infection." (PMID 33224900, 2020). "However, despite the robust Ply-driven autophagic targeting of SPN, most of Gal8 positive PCVs, showing association with LC3 and LAMP1, failed to accumulate LysoTracker till delayed hours post infection." (PMID 30011336, 2018). "Although it is assumed that loss of the capsule is associated with decreased virulence, it has been reported that increased production of SPN and SLO results in high virulence even without the capsule in a mouse infection model." (PMID 38587390, 2024).
cancer (27 papers, 2007 to 2025). A tumor composed of atypical neoplastic, often pleomorphic cells that invade other tissues. "The advantage of using a broadly expressed antigen such as SPN, whose expression is also maintained in most blood-cancer-derived cell lines, is to not only address relapse in AML but also potentially extend the product to patients with other blood cancers." (PMID 40191207, 2025). "There are few studies on the biological function of SPN in the progression of cancers, and only one study discussing the role of aberrant CD43 glycosylation as a cancer biomarker." (PMID 34001147, 2021). "We characterized an oncogenic mutation of SPN located in the PDZ domain since cells that overexpress SPN-A566V presented a clear increase in some tumorigenic and cancer stem cell properties." (PMID 33537097, 2021). "Therefore, the fact that the loss of SPN causes an increase in the stem cell phenotype could explain why tumors with low SPN levels have a worse prognosis since poor response to chemotherapy and relapse are associated with a greater number of cancer stem cells (CSCs) 15,17,22,23." (PMID 33537097, 2021). "Moreover, overexpressed miR-129-5p remarkably reduced SPN expression in cancer cells, weakened the promoting effect of SPN on cell proliferation, migration, invasion and cell cycle progress, and led to enhanced cell apoptotic activity." (PMID 34001147, 2021). "Hence, exploring the regulatory role of SPN in ccRCC will provide a theoretical basis for SPN acting as a cancer regulatory factor." (PMID 34001147, 2021). "Among the differentially expressed genes in metastatic samples, we found 7 of 30 genes (MAPK13, XIAP, AHR, SPN, TER1, EMP2, NDUFC2) were cancer-related." (PMID 28009993, 2017).
hematological cancers (2 papers, 2019 to 2025). "Thus, our findings suggest that SPN may play a protective role in hematological cancers (particularly AML), promoting evasion of CD3 bsAb-mediated T cell killing." (PMID 31882897, 2019).
psychiatric disorder (1 paper, 2020). A disorder characterized by behavioral and/or psychological abnormalities, often accompanied by physical symptoms. "Moreover, future cooperative projects incorporating basic research using experimental animals and clinical research during child development will advance our understanding of how SpN activity affects the development of neurodevelopmental and psychiatric disorders during corticogenesis." (PMID 32265668, 2020).
SPN also shares sentences with these, for which no sentence is quoted: leukemia (22 papers); lymphoma (19); atherosclerosis (6); Chronic Lymphocytic Leukemia (6); bacterial infection (4); colitis (4); follicular lymphoma (4); MALT lymphoma (4); mantle cell lymphoma (4); T-cell lymphoma (4); diffuse large B-cell lymphoma (3); myeloid sarcoma (3); acute leukemia (2); acute lymphoblastic leukemia (2); Arthritis (2); Autoimmunity (2); Burkitt lymphoma (2); colorectal cancer (2); Hypertension (2); influenza (2); lymphoblastic lymphoma (2); lymphoid tumors (2); myocarditis (2); non-Hodgkin lymphoma (2); psoriasis (2); Sepsis (2); Stroke (2); abdominal aortic aneurysm (1); abscess (1); adenoid cystic carcinoma (1).
A further 69 diseases each share a sentence with SPN in 1 paper.